HDAC8 (histone deacetylase 8)
Diseases named in the same sentence as HDAC8 in open-access papers (continued):
Sharing a sentence is not in itself a finding about the gene and the disease.
cancer (continued). "We analyzed the co-occurrence of gain of HDAC8 copy numbers with gain of copy numbers in genes involved in replication stress and oncogenic pathways for all cancer types included in The Cancer Genome Atlas (TCGA) pan-cancer initiative." (PMID 39436709, 2024). "Taken together, these results strengthen our concept that cotargeting HDAC8 and checkpoint kinases could be an efficacious and well-tolerated strategy for cancer therapy." (PMID 39436709, 2024). "Various studies have demonstrated the pathological role of HDAC8 in diseases, including cancer." (PMID 36831463, 2023). "Therefore, additional studies need to be conducted to understand the potential contribution of HDAC8 inhibition in the anti-cancer effect of JBI-097, that are beyond the scope of the manuscript." (PMID 36595522, 2023). "Nevertheless, numerous studies support the tumorigenic role of HDAC8 and confirmed that genetic ablation or pharmacological inhibition of HDAC8 reduces cell proliferation, suppresses colony formation, and induces cell cycle arrest in cancer." (PMID 36231123, 2022). "Therefore, further studies are required to increase our understanding of HDAC8 in non-cancer diseases." (PMID 36231123, 2022). "Thus, the present results suggest the possibility that autophagy is a key mechanism by which the HDAC8 gene preferentially kills cancer cells." (PMID 36575468, 2022). "In addition, Ser39, Ser43, and Ser63 of HDAC8 are shown to be phosphorylated by activated AMPK under the condition of glucose deprivation in cancer cells, connecting cancer survival with glycogen pathway via overexpression of phosphoglucomutase 1 (PGM1)." (PMID 35659740, 2022). "HDAC8 has been reported to be involved in metastasis of other cancers besides BC." (PMID 36231123, 2022). "Therefore, the inhibition of HDAC8 as an epigenetic tool has emerged as an effective treatment strategy for cancer therapy." (PMID 36575468, 2022). "As evidence highlighted that simultaneous inhibition of HDAC6 and HDAC8 could lead to synergistic therapeutic effects in cancer and could be beneficial in different pathologic conditions, several dual HDAC6/8 inhibitors have been recently disclosed." (PMID 36077415, 2022). "Studies of HDAC8 are heavily concentrated on its role in cancer progression." (PMID 36231123, 2022). "As the most recently identified class I HDAC, however, a comprehensive understanding of HDAC8 in cancer remains unclear." (PMID 35955780, 2022). "In addition, detyrosination of α-tubulin, an important marker of migration and invasion of cancer cells, is decreased upon HDAC8 inhibition in BC cells." (PMID 36231123, 2022). "However, only very limited knowledge exists about the regulation of HDAC8, an established target in multiple types of cancer." (PMID 30292946, 2019). "Among the various HDAC enzymes, HDAC8 is an emerging target in cancer research." (PMID 30687400, 2018). "Based upon the expression pattern of HDAC6 in different cancer cell lines, we presume its role in deacetylating ac-alpha tubulin in HeLa might be taken over by HDAC8 due to its significant overexpression compared to HDAC6." (PMID 29716651, 2018). "The role of HDAC8 in normal and cancer cells remains unexplored." (PMID 26200462, 2015). "Given our results showing that HDAC8 activity is crucial for maintaining replication fork stability in conjunction with checkpoint kinases, we hypothesized that HDAC8 is likely to be maintained and coamplified with components of the replication stress pathways in cancers." (PMID 39436709, 2024). "Using the promising cancer target human histone deacetylase 8 as an example, we present a robust method that calculates concentration-dependent apparent rate constants for the inhibition or inactivation of HDAC8 from dose–response curves recorded after different pre-incubation times." (PMID 38891780, 2024).
cancer (continued). "Interestingly, analysis of the Broad Institute Cancer Dependency Map (DepMap) revealed that DCAF15 and the histone deacetylase HDAC8 are top cancer co-dependencies, suggesting that these proteins may function together in the same cohesin recycling process." (PMID 38961054, 2024). "Furthermore, HDAC8 has been connected to RA signaling in cancer." (PMID 30890583, 2019). "We also observed that HDAC8 expression was positively correlated with CSNK2A1, CSNK2A2, and CSNK2B in multiple cancer types in public databases." (PMID 40013761, 2025). "Compound 7p, in particular, displayed strong affinity for key cancer-related targets such as HSP90, IGF1R, HDAC2, CDK6, HDAC8, and PIK3CA, all of which are involved in tumour proliferation, survival, and metastasis." (PMID 41463373, 2025). "At the expression level, a positive correlation between HDAC8 and CHK1 or ATR was also found in pan-cancer datasets, suggesting coregulation between these genes in many tumor types." (PMID 39436709, 2024). "Histone deacetylase 8 (HDAC8) and TLE4 genes are the targets of miR-93, which functions as a cancer inhibitor in CSCs." (PMID 39170516, 2024). "Accordingly, the pharmacological inhibition or the genetic ablation of HDAC8 suppresses the transcriptional activity of HIF-1 and demonstrates anti-cancer effects." (PMID 36831463, 2023). "Dual inhibition of HDAC8 and MMP-2 is a potent anti-cancer therapeutic strategy for solid and hematological cancers." (PMID 36231123, 2022). "HDAC8, another member of the HDAC family, has recently gained attention as a novel target for cancer therapy." (PMID 35955780, 2022). "We explored here the expression profile of HDAC family via Oncomine database, which indicated that HDAC1, HDAC2, HDAC3, HDAC7, HDAC8, and HDAC9 expressed highly in pan‐cancer at transcriptional level." (PMID 34308568, 2021). "HDAC8 also is involved in cellular invasion and expression of the MMP-9 gene in human cancer cells[30 ▶]." (PMID 32429642, 2020). "The genes in that amplified segment are ABBC10, a transmembrane transporter with implication on anti-cancer agent transfer and ZNF318, coding for the best substrate for deacetylation enzymes (HDAC8)." (PMID 33168853, 2020). "All escapees (normal or “cancer-specific”) showed low levels of DNA methylation at their promoters (e.g., KDM5C, HDAC8)." (PMID 25653311, 2015). "The most resistant enzyme was HDAC8, which was only partly inhibited by 400 nM TSA, a concentration that fully inhibits cancer cell viability." (PMID 22158273, 2012). "HDAC8 alters cancer cell proliferation, cell cycle, and differentiation, and HDAC9 could mediate cancer cell proliferation, autophagic flux, and chemoresistance." (PMID 40283998, 2025). "We also analyzed the correlation between CSNK2B expression and HDAC family‐related genes in the TIMER2.0 public database of multi‐cancer, and we found that the expression of CSNK2B showed a positive correlation with HDAC1, HADC2, HDAC5, HDAC6, and HDAC8 in LUAD and LUSC." (PMID 40013761, 2025). "Like many of the other HDACs, HDAC8 plays a crucial role in various aspects of cancer development by interacting with histone and non-histone proteins." (PMID 36831463, 2023). "In addition, miR-34a is involved in the regulation of EMT progression, cancer stemness and M2 macrophage polarization in TNBC, while miR-483-3p suppresses TNBC proliferation and progression by targeting HDAC8." (PMID 33088216, 2020). "An anomalous histone acetylation, and consequently an alteration in the expression of HDACs, is related to cancer Likewise, an overexpression of HDAC1 and HDAC2 has been found in LC, and HDAC8 knockdown leads to the inhibition of cell proliferation in lung and other types of cancer." (PMID 30759767, 2019).
cancer (continued). "Of note, the combination treatment of crizotinib with the HDAC8 inhibitor affected neither untransformed cells, nor other embryonic cancer cell models." (PMID 29515255, 2018). "HDAC8 is a class I HDAC involved in various diseases, including cancer." (PMID 28390197, 2017). "Among them, the modifications in HDAC8 expression do not affect cancer cell proliferation, and the expression of other class I HDACs in CCA has not been studied." (PMID 29245911, 2017). "However, we noted that some genes subject to XCI (i.e., only expressed from the Xa) in cancer cell lines, nevertheless showed low promoter methylation (e.g., TBL1X in SK-BR-3 cells or HDAC8 in ZR-75-1)." (PMID 25653311, 2015). "As our results suggest, dual inhibitors targeting both HDAC6 and HDAC8 may prove to be an effective anti-cancer agent as they would decrease the undesirable cytotoxic side effects from having to use multiple inhibitors while still providing the anti-cancer benefits of inhibiting HDAC6 and HDAC8." (PMID 35955780, 2022). "For “cancer-specific” escapees (TBL1X in ZR-75-1, HDAC8 in MDA-MB-436 and SK-BR-3), no obvious systematic correlation between local H3K27me3 levels and escape/silencing could be seen." (PMID 25653311, 2015).
tumor (84 papers, 2007 to 2026). "The diagnostic value of HDAC8, as a potential tumor marker, for the differentiation of nTNBC from TNBC subjects was investigated." (PMID 32429642, 2020). "Furthermore, loss of HDAC8 activity sensitized tumor cells to chemotherapeutic treatments, even at low doses." (PMID 35016723, 2022). "Interestingly, loss of HDAC8 in pG-2 cells potentiated the effect of the chemotherapy on tumor cell proliferation." (PMID 35016723, 2022). "In addition, in the TNBC group, there was a significant association between the HDAC8 overexpression and tumor characteristics, including tumor size (p = 0.039), lymphatic invasion (p = 0.01), tumor grade (p = 0.02), and perineural invasion (p < 0.05)." (PMID 32429642, 2020). "However, in the TNBC group, a significant association was found between the increased HDAC8 expression and tumor characteristics, including tumor size (p = 0.039), lymphatic invasion (p = 0.01), tumor grade (p = 0.02), and perineural invasion ( (p = 0.014)." (PMID 32429642, 2020). "Histone deacetylase 8 is also key to tumour cell growth in vitro, but instead of impacting on histone acetylation, HDAC8 associates with cytoskeleton proteins and may play a role in smooth muscle contractility." (PMID 18000499, 2007). "Among the family of HDACs, HDAC8 (a class I HDAC) plays key roles in NB, as its expression has been associated with enhanced tumor progression, metastasis, and poor clinical outcomes." (PMID 40507292, 2025). "Elevated HDAC8 expression has been reported in hepatocellular carcinoma, where it promotes tumor growth and confers resistance to chemotherapy." (PMID 40332124, 2025). "Among the HDAC family, HDAC4 and HDAC8 have gained significant attention because of their distinct roles in tumor biology." (PMID 40332124, 2025). "Compared to HDAC8 WT, the tumor‐promoting effect of the HDAC8 C244S mutant was abolished in HCC proliferation." (PMID 40787880, 2025). "The ability of sunitinib in combination with HDAC8 knockdown or HDAC8 inhibitor treatment to inhibit xenograft tumor growth was diminished after 13 days." (PMID 39073752, 2024). "Compared to other groups, the aCD20@ExoCTX/siPDK4 group significantly reduced the green and yellow fluorescence intensities of PDK4 and p-HDAC8 in mouse tumor tissues, indicating that the expression of PDK4 and p-HDAC8 was inhibited in vivo." (PMID 39004737, 2024). "In the preclinical model of HCC, selective inhibition of HDAC-8 increased tumor inhibition of CD8+ T cells, and enhanced eradication of HCC by anti-PD-L1 therapy, with good safety." (PMID 37304265, 2023). "In an A549 tumour mouse model, 48 induced HDAC8 degradation and tumour regression, especially, in combination with irradiation." (PMID 37667522, 2023). "In PAC cases, HDAC8 immunoreactivity was high, mainly cytoplasmic, and focally nuclear, in 40% of tumor cells." (PMID 37887281, 2023). "HDAC8 is also deeply involved in the process of immune evasion and drug resistance, which are crucial for tumor progression." (PMID 36231123, 2022). "Together, these data strongly indicate a tumor-promoting role of HDAC8 through a repressive function on the MET program in BLBC patients." (PMID 35016723, 2022). "HDAC8 appears to be an attractive target for anticancer drug development since HDAC8 plays an explicit tumor-relevant role in CRC." (PMID 36575468, 2022). "Subsequent analyses of human BLBC patient datasets and cell lines established HDAC8 as the most promising factor sustaining tumor cell viability." (PMID 35016723, 2022).
tumor (continued). "Collectively, our findings identified HDAC8 as a druggable factor supporting tumor cell survival to conventional chemotherapies by promoting the EMT transcriptional program in BLBC lesions." (PMID 35016723, 2022). "Our present investigations in BLBC malignancies identified an alternative tumor-promoting function by HDAC8 supporting the activation of EMT transcriptional program." (PMID 35016723, 2022). "In line with the knockdown results, HDAC8 inhibition sensitized the tumor cells to the cytotoxic treatment in all cases." (PMID 35016723, 2022). "Several studies have investigated the molecular mechanism of HDAC8-induced tumor cell proliferation." (PMID 36231123, 2022). "In terms of tumor immunity, HDAC8, 9, and 10 have been reported to be related to the expression of immune checkpoint." (PMID 34880761, 2021). "HDAC1 (p = 0.05), HDAC3 (p = 0.02), the second probe of HDAC5 (p = 0.04) and of HDAC7 (p = 0.03), and HDAC8 (p = 0.004), were increased in tumours with 8q gain, while HDAC11 was decreased (p = 0.002)." (PMID 33316946, 2020). "Expression of HDAC1 (p = 0.02), HDAC3 (p = 0.04), HDAC4 (p = 0.001), as well as HDAC8 (p < 0.001) was significantly higher in M3 tumours compared to D3 tumours." (PMID 33316946, 2020). "Our results confirmed that the regulation of PKM2 entry into the nucleus by HDAC8 is essential for the growth of tumor cells." (PMID 33279948, 2020). "Despite the normal expression of HDAC8 in healthy organs, its expression in tumor tissues is up-regulated 35,36." (PMID 31908740, 2019). "Examinations of the associations between HCC progression and HDAC8 expression revealed a positive correlation of HDAC8 expression with HCC tumor size, invasion, and poor staging." (PMID 29301348, 2018). "The combinatorial inhibition of ALK and HDAC8 also decreased tumor growth in an in vivo zebrafish xenograft model." (PMID 29515255, 2018). "The efficacy of HDAC8 inhibition, crizotinib and the combination was assessed by evaluating tumor volume change, quantified via semi-automated image analysis, from day one (start of treatment) to day three (end of experiment) post-implantation." (PMID 29515255, 2018). "The expression correlation between AHR and HDAC8 was further verified by immunofluorescence staining of HCC patient tumor tissue." (PMID 27283490, 2017). "In 8 randomly selected HCC samples obtained from patients in the high AHR group, the increased HDAC8 expression correlated with the expression pattern of AHR when compared with those of paired tumor-adjacent, normal tissues." (PMID 27283490, 2017). "HDAC protein expression was then assayed by Western blot (WB), and the expression of HDAC2, HDAC3, and HDAC8 were higher in CCA tissues compared with paired non-tumor tissues (P<0.05)." (PMID 27705912, 2016). "This study demonstrates superiority of selective HDAC isozyme targeting versus pan-HDAC inhibition in terms of toxicity and efficacy in a tumor model that is dependent on HDAC8." (PMID 25695609, 2015). "The identification of HDAC8-specific substrates is still of major interest and would be the best tool for HDAC8 inhibitor on-target validation in tumor tissue." (PMID 25695609, 2015). "Taken together, selective inhibition of HDAC8 enhanced differentiation, reduced tumor growth and induced cell death in vitro and in vivo." (PMID 25695609, 2015). "R306465 showed potent inhibition of HDAC1 and HDAC8 in vitro and specifically induced histone acetylation in tumour cells." (PMID 18000499, 2007). "Activity towards HDAC1–3 and HDAC8 has been demonstrated to be essential for tumour cell proliferation." (PMID 18000499, 2007). "In addition, the study by Wang and co-authors (2018) shows that conditional deletion of HDAC8 in Foxp3+ Treg cells or the use of HDAC8 inhibitors impairs Treg function and promotes anti-tumor immunity." (PMID 40861448, 2025).